RSPH1 (radial spoke head component 1)
Description:
Functions as part of axonemal radial spoke complexes that play an important part in the motility of sperm and cilia.
Synonyms: CT79; TSA2; TSGA2; FLJ32753; RSP44; RSPH10A; CILD24
Tractability: Small molecule: a structure with a bound ligand is known.
Gene: Protein-coding gene on chromosome 21 (42,472,486 to 42,496,366, reverse strand). Ensembl gene ENSG00000160188.
Subcellular location: Cytoplasm; Chromosome; Cytoplasm, cytoskeleton, cilium axoneme; Cytoplasm, cytoskeleton, flagellum axoneme
Subcellular location (Human Protein Atlas): Basal body; Centrosome; Mid piece; Acrosome
Gene Ontology:
Molecular function: protein binding
Biological process: axoneme assembly; cilium movement; flagellated sperm motility; spermatid development; microtubule-based process
Cellular component: cytosol; motile cilium; nucleus; 9+2 motile cilium; axoneme; chromosome; cilium; cytoplasm; radial spoke; radial spoke head; sperm flagellum; condensed nuclear chromosome; meiotic spindle; outer dense fiber; radial spoke head 1; radial spoke head 3
Genetic constraint (gnomAD): Loss-of-function variants: 16 observed, 29.99 expected, observed/expected ratio (o/e) 0.53, 90% interval 0.36 to 0.81. The upper end of that interval is the gene's LOEUF score, 0.81, which puts it in group 3 of 6, group 1 being the genes least tolerant of losing a copy. Missense variants: 310 observed, 306.64 expected, observed/expected ratio (o/e) 1.01, 90% interval 0.92 to 1.11. Synonymous variants: 103 observed, 120 expected, observed/expected ratio (o/e) 0.86, 90% interval 0.73 to 1.01.
Gene-disease validity (ClinGen):
ClinGen rates the evidence that RSPH1 causes each of these diseases.
primary ciliary dyskinesia 24 (autosomal recessive): Definitive.
Homologues: Orthologues: chimpanzee RSPH1 (98% identical), macaque RSPH1 (89% identical), pig RSPH1 (78% identical), mouse Rsph1 (77% identical), dog RSPH1 (77% identical), rat Rsph1 (76% identical), guinea pig RSPH1 (75% identical), zebrafish RSPH1 (48% identical), Drosophila melanogaster Rsph1 (36% identical). Paralogues in human: RSPH10B (25% identical), RSPH10B2 (25% identical), MORN1 (22% identical), ALS2CL (21% identical), MORN3 (20% identical), SETD7 (19% identical), MORN2 (13% identical).
Diseases named in the same sentence as RSPH1 in open-access papers:
RSPH1 is named in the same sentence as 18 diseases in open-access papers, as found by Europe PMC text mining. Sharing a sentence is not in itself a finding about the gene and the disease. The quoted sentences say what the papers report.
primary ciliary dyskinesia (6 papers, 2014 to 2024). A rare, genetically heterogeneous, primarily respiratory disorder characterized by chronic upper and lower respiratory tract disease. "Enriched genes include dynein light chain roadblock-type 2 (Dynlrb2), a target of forkhead box J1 (FOXJ1) that regulates motile ciliogenesis, and radial spoke head 1 homolog (Rsph1) mutations are a cause of primary ciliary dyskinesia." (PMID 32298260, 2020). "Previous studies have found that mutations in RSPH1 and CFAP61 cause disintegration of the sperm flagellar structure and primary ciliary dyskinesia." (PMID 37601242, 2023). "The association of cilia dysfunction and SI, formerly described as Kartagener syndrome, may occur even in less than 50% of all PCD as some defects, in particular those associated with mutations in HYDIN, RSPH9, RSPH4A, and RSPH1 genes, do not cause SI." (PMID 28649564, 2017).
male infertility (4 papers, 2016 to 2023). The inability of the male to effect fertilization of an ovum after a specified period of unprotected intercourse. "Male infertility caused by the RSPH1 or RSPH9 variant has been clarified." (PMID 35812741, 2022). "We demonstrate for the first time that pathogenic variants in RSPH1 and RSPH9 cause male infertility due to sperm cell dysmotility and abnormal flagellar RSPH1 and RSPH9 composition." (PMID 36873931, 2023). "RSPH1 is a major component of the radial spoke, and inactivation of this gene results in disintegration of the sperm flagellar structure and male infertility." (PMID 37601242, 2023). "Variants in RSPH1, RSPH3, and RSPH9 genes have been reported to cause male infertility in humans." (PMID 35812741, 2022). "RSPH1 is involved in primary ciliar dyskinesia (PCD), a disorder with male infertility due to dysmotility of spermatozoa and reduced fertility or a history of ectopic pregnancies in affected women." (PMID 27716277, 2016).
infertile (3 papers, 2023). "In our population, the patient with the RSPH4 mutation was infertile and the three sisters with the RSPH1 mutation, despite not having performed fertility tests, were unable to conceive and chose to adopt." (PMID 36980814, 2023). "Some of the male patients carrying RSPH1 and RSPH3 mutations were infertile." (PMID 38091523, 2023). "We identified ten infertile male individuals with pathogenic variants in CCDC39 (one) and CCDC40 (two) encoding ruler proteins, RSPH1 (two) and RSPH9 (one) encoding radial spoke head proteins, and HYDIN (two) and SPEF2 (two) encoding CP-associated proteins, respectively." (PMID 36873931, 2023).
Neonatal respiratory distress (2 papers, 2017 to 2022). Respiratory difficulty as newborn. "Conversely, individuals with biallelic MNS1, DNAH9, CFAP53 or RSPH1 mutations have a lower prevalence of neonatal respiratory distress and a later and milder onset of respiratory symptoms." (PMID 36583018, 2022). "Although persons with these variants can have unexplained neonatal respiratory distress, the splice site variation in RSPH1 is associated with a lower prevalence of neonatal respiratory distress, later onset of daily wet cough, and better adult lung function than other forms of PCD." (PMID 28793908, 2017).
situs inversus (2 papers, 2022). A congenital condition in which there is complete right-to-left reversal of the position of the major thoracic and abdominal organs (that is, they are arranged in a mirror image of the normal positioning). "Mutations in proteins (e.g., HYDIN, RSPH1) that affect the central pair, which are not present in nodal cilia, cause PCD without causing the situs abnormalities associated with PCD (e.g., situs inversus, situs ambiguous)." (PMID 35163670, 2022). "Normal visceral placement is driven by the dynein of nodal cilia, so patients with gene mutations encoding non-dynein structural components such as RSPH1, RSPH3, and HYDIN have not been reported for situs inversus." (PMID 36583018, 2022).
asthenozoospermia (1 paper, 2023). "Here, we show in both RSPH1-mutant individuals affected male fertility due to asthenozoospermia, through a combination of an increased proportion of immotile and dysmotile sperm with non-progressive or slow-progressive patterns." (PMID 36873931, 2023).
asthma (1 paper, 2022). "In addition, one study found that asthma patients with the RSPH1 mutation had significantly higher levels of nasal-exhaled nitric oxide than other asthma patients." (PMID 36159986, 2022).
Hearing impairment (1 paper, 2023). A decreased magnitude of the sensory perception of sound. "This is in contrast to defects in other radial spoke genes such as RSPH1 that tend to associate with milder lung disease, situs solitus, and, occasionally, middle ear disease or hearing impairment." (PMID 37892643, 2023).
Hydrocephalus (1 paper, 2023). Hydrocephalus is an active distension of the ventricular system of the brain resulting from inadequate passage of CSF from its point of production within the cerebral ventricles to its point of absorption into the systemic circulation. "RSPH1, RSPH4A, and RSPH9 knockout mouse models recapitulated the PCD phenotypes such as hydrocephalus and impaired mucociliary clearance." (PMID 38091523, 2023).
varicocele (1 paper, 2015). A condition characterized by the dilated tortuous veins of the spermatic cord with a marked left-sided predominance. "We found RSPH1 underexpressed with low abundance in the unilateral varicocele group." (PMID 25890347, 2015).
tumor (4 papers, 2017 to 2025). "CD24, CLDN3, WFDC2, and TACSTD2 genes were present in all the tumour clusters of all samples, and the genes C1orf194, C20orf85, MS4A8, ODF3B, RSPH1, and TPPP3 appear to be co‐expressed." (PMID 41160707, 2025).
RSPH1 also shares sentences with these, for which no sentence is quoted: infection (2 papers); cancer (1); ciliopathies (1); Down syndrome (1); lung disease (1); middle ear disease (1); Respiratory distress (1).